TLR2 (toll like receptor 2)
Diseases named in the same sentence as TLR2 in open-access papers (continued):
Sharing a sentence is not in itself a finding about the gene and the disease.
Insulin resistance (continued). "Thus, it has been described that palmitate through TLR2 may induce insulin resistance in myotubes, inducing activation of NF-κB, JNK and p38 and the impairment of vasodilator actions of insulin." (PMID 26055507, 2015). "Therefore, RP105 or MD-1 KO mice may impair both TLR4- and TLR2-mediated promotion of adipose tissue inflammation and insulin resistance." (PMID 24064574, 2013). "In addition, a reduction in Treg cells in eWAT from TLR2 KO mice may also contribute to the increased insulin resistance in these mice." (PMID 24064574, 2013). "Likewise, TLR2 has been shown as an important modulator of insulin resistance." (PMID 23482058, 2013). "Thus, we have found that the insulin resistance presented by TLR2 KO mice could be explained by the increased LPS serum levels, which led to increased activation of TLR4 in muscle, liver and adipose tissue, and increased phosphorylation of JNK, but not of IKK." (PMID 23482058, 2013). "Furthermore, TLR2, following ligation with specific ligands, can activate signal transduction, promote interleukin (IL)-6 production, and mediate initial events related to fatty acid-induced insulin resistance in muscle." (PMID 23213270, 2012). "Palmitic acid, one of the most abundant components of PO, was associated with inflammation via the activation of toll-like 2 and 3 receptors (TLR2 and TLR3) and nuclear factor kappa b (NF-κB)-mediated cytokine synthesis, insulin resistance, and NPY expression." (PMID 39125278, 2024). "FFAs have been shown to activate Toll-like receptor 2 (TLR-2), TLR-4/nuclear factor-kappaB (NF-κB), and c-Jun N-terminal kinase (JNK) signaling pathways, thereby promoting inflammation and insulin resistance." (PMID 38001499, 2023). "Among the TLRs, TLR2 and TLR4 expression have been shown to be increased in conventional insulin resistance target tissues like skeletal muscle and adipose tissue of type 2 diabetic subjects." (PMID 37434784, 2023). "TLRs, particularly TLR2 and TLR4, are involved in the development and progression of insulin resistance and diabetic complications such as diabetic nephropathy and vascular damage." (PMID 36589440, 2022). "Studies from our department in primary astrocytes from TLR2/4 knock-out mice have shown increased phosphorylation of p-Akt and p-GSK after insulin stimulation and knockout animals were protected from brain insulin resistance on high-fat diet." (PMID 33047031, 2020). "The expression of TLR2 and TNF-α was increased in visceral adipose tissue by a HFD as a development of insulin resistance." (PMID 31582899, 2019). "Activation of TLR2 and TLR4 with fatty acids contributes to NF-κB activation, increased inflammation, and insulin resistance." (PMID 22384159, 2012). "The inhibition of TLR2 expression can rescue cells from the activation of MAPK8 and improve insulin resistance." (PMID 23213270, 2012). "The role of TLR2 and TLR4 has been suggested in conventional insulin resistance (IR) target tissues like skeletal muscle and adipose tissue of Type 2 diabetes subjects." (PMID 23191980, 2012). "The results of the other study exhibited that probiotic intake in TLR2−/− mice by increasing lipopolysaccharides and then TLR/JNK pathway activation resulted in downregulating insulin signaling pathway and inducing insulin resistance in the liver and muscle tissue of animals." (PMID 38504163, 2024). "White adipose tissue stresses or lipopolysaccharides increase NF-κB and c-Jun N-terminal kinase signaling, upregulate the production of inflammatory cytokines such as TNF-α and IL-6, and promote insulin resistance in adipocytes and macrophages via TLR4/TLR2 activation." (PMID 38292473, 2024). "Previous studies have shown that TLR2/4 and JNK signaling pathways play a pivotal role in activating CD11c (+) myeloid proinflammatory cells, which further promotes inflammation and subsequent insulin resistance in cells." (PMID 30755828, 2019).
Insulin resistance (continued). "TLR2 is crucial for diet-induced metabolic syndrome because mice lacking TLR2 are substantially protected from diet-induced adiposity and insulin resistance." (PMID 23213270, 2012). "The major finding of the present study is that TLR2 expression, after stimulation with peptidoglycan, showed significant correlation with insulin resistance in patients with RA in the absence of hyperglycemia." (PMID 23213270, 2012). "TLR2 still plays a role in the development of insulin resistance in patients with RA even in the absence of hyperglycemia, which is a well-known risk factor for metabolic syndrome." (PMID 23213270, 2012). "However, the relevance of the effect of TLR2 and TLR4 on conditions such as insulin resistance is not entirely clear, with some studies indicating that TLR2 is a protective factor and others indicating the opposite." (PMID 40076851, 2025). "Additionally, mice lacking TLR2 are protected from diet-induced adiposity, insulin resistance, hypercholesterolemia, and hepatic steatosis, suggesting that TLR2 plays a critical role in the development of diet-induced metabolic syndrome." (PMID 40558558, 2025). "Mice lacking TLR2 are substantially protected from diet-induced adiposity, insulin resistance, hypercholesterolemia, and hepatic steatosis and TLR2 deletion was associated with attenuation of adipocyte hypertrophy as well as diminished macrophage infiltration and inflammatory cytokine expression." (PMID 23191980, 2012). "Overall, these results suggest that the overexpression of TLR2 and TLR4 on both PBMCs and adipose tissues together with the enhanced production of proinflammatory cytokines may pave way for the development of insulin resistance in obese individuals, leading to type 2 diabetes." (PMID 23191980, 2012). "In addition to inflammation that causes modification of the gut microbiota (higher Bacteroidetes and Firmicutes, lower Proteobacteria), insulin resistance (in absence of TLR2) is attributed to increased lipopolysaccharides- (in serum) mediated activation of TLR4 in liver muscle and adipose tissue." (PMID 36556351, 2022). "The siRNA-mediated reduction in TLR4, but not TLR2, in livers of LKO mice significantly ameliorated the insulin resistance." (PMID 24614850, 2014). "Although numerous studies have demonstrated that TLR2- and TLR4-dependent signaling are involved in the development of insulin resistance, data on a similar mechanism in the pathogenesis of insulin resistance in RA patients are still lacking." (PMID 23213270, 2012). "The results demonstrating the close relationship between HOMA index and TLR2 expression in monocytes and inflammatory cytokines such as TNF-α and IL-6 could provide therapeutic interventions against insulin resistance in nondiabetic RA patients." (PMID 23213270, 2012).
rheumatoid arthritis (75 papers, 2005 to 2025). A chronic, systemic autoimmune disorder characterized by inflammation in the synovial membranes and articular surfaces. "TLR2 and its signaling have been implicated in a variety of inflammatory diseases such as rheumatoid arthritis, inflammatory bowel disease, asthma, and multiple sclerosis." (PMID 37569837, 2023). "Specifically, the TLR signaling pathway has been implicated in rheumatoid arthritis (RA) in that TLRs were increased in multiple immune cell types as TLR-2 and TLR-4 ligand responses were increased in RA patients." (PMID 35008717, 2021). "The distinct roles of TLR2 and TLR4 in immunomodulation was further emphasized by findings that TLR2-deficient mice experienced increased joint inflammation in preclinical rheumatoid arthritis (RA) models, while TLR4-deficient mice were more resistant." (PMID 21435210, 2011). "Moreover, for TH22/17-associated autoimmune conditions including rheumatoid arthritis, TLR2, TLR4, and TLR5 modulation holds potential for managing these disorders." (PMID 37760825, 2023). "Additionally, polymorphisms in human TLR2 have been strongly implicated in the development of several diseases, including rheumatoid arthritis, type I diabetes, and asthma." (PMID 35941134, 2022). "Even though the observed EV-based stimulation of TLR2 may indicate possible beneficial effects, human Tlr2 polymorphisms have complex roles in several diseases, including rheumatoid arthritis, type I diabetes or colorectal cancer." (PMID 33408714, 2020). "TLR2/4 receptors are implicated in several pathological conditions such as rheumatoid arthritis." (PMID 27245842, 2016). "Activation of TLR2 has been implicated in oncogenesis, autoimmune diseases (AD) including multiple sclerosis (MS), rheumatoid arthritis (RA), systemic lupus erythematosus (SLE), Sjogren’s syndrome (SS), and Systemic sclerosis (SSc), as well as in neurological dysfunction/disorders." (PMID 28036046, 2016). "M2 macrophages from healthy donors or patients with rheumatoid arthritis showed reduced anti-inflammatory activity in the presence of abundant TLR2." (PMID 37569837, 2023). "In autoimmune diseases characterized by TH22-/TH17-dominated immune responses, such as rheumatoid arthritis and Arthus reactions, the expression of TLR2, TLR4, and TLR5 is upregulated." (PMID 37760825, 2023). "M2-polarized macrophages in rheumatoid arthritis patients displayed an impaired anti-inflammatory activity under TLR2 engagement." (PMID 36778150, 2023). "Ex-vivo studies, conducted on microvascular endothelial cells and rheumatoid arthritis (RA) explants of whole synovial tissue have shown that TLR2 induces angiogenic tube formation and ANGPT2 expression." (PMID 35877427, 2022). "For example, toll-like receptor (TLR) 7 signaling promotes autoantibody production in lupus, whereas TLR2/4 contribute to rheumatoid arthritis, and TLR2/4/9 contribute to multiple sclerosis pathogeneses." (PMID 36499283, 2022). "Each of three pathway categories legionellosis, amoebiasis and rheumatoid arthritis was enriched by two hub-DEGs (TLR2 and CXCL2)." (PMID 35277538, 2022). "ZFTG can effectively regulate the levels of inflammatory indicators such as CRP in the blood of rats by mediating the TLR2/4-NF-κB signaling pathway and relieving the symptoms of arthritis in the feet of rats with rheumatoid arthritis." (PMID 36188596, 2022). "There is strong evidence that synovial macrophages and chondrocytes express TLR2 and TLR4, while TLR4 senses more DAMPs than TLR2 in both OA and rheumatoid arthritis (RA)." (PMID 36032081, 2022). "The blockade of TLR2 by OPN301 (an IgG1 monoclonal anti-TLR2 antibody) in cells of patients with rheumatoid arthritis was found to decrease the production of TNF, IL-1β and IFN-y after stimulation with Pam3Cysk4 (a TLR2 agonist)." (PMID 34691019, 2021).
rheumatoid arthritis (continued). "TLR2 is widely investigated in the pathogenesis of autoimmune diseases including rheumatoid arthritis, systemic lupus erythematosus, systemic sclerosis, Sjogren’s syndrome, psoriasis, multiple sclerosis, and autoimmune diabetes." (PMID 34372877, 2021). "For example, TLR2 and 4 synergize in rheumatoid arthritis-derived synoviocytes, rheumatoid arthritis, sarcoidosis, systemic lupus erythematosus, systemic sclerosis, Sjogren’s syndrome, psoriasis, multiple sclerosis and autoimmune diabetes." (PMID 32629865, 2020). "For example, perspectives of TLR2 (T cell and B cell signaling in rheumatoid arthritis pathway) agonists in vaccine-adjuvant immunotherapy for cancer have been reported." (PMID 31258820, 2019). "Increased TLR2 expression on monocyte subsets in patients with active rheumatoid arthritis, the mucosa of duodenal samples of patients with coeliac disease (CD), and PBMCs of those with autoimmune thyroid disease have also been reported." (PMID 31611734, 2019). "Activation of both TLR2 and TLR4 receptors are linked to increased expression of RANKL in fibroblast-like synoviocytes in rheumatoid arthritis." (PMID 27308827, 2016). "Some publications describe the expression of TLRs in rheumatoid arthritis and note that patients demonstrate higher expression of TLR2, 3, and 4 on fibroblasts from the synovial tissue." (PMID 24692849, 2014). "Our finding is consistent with a previous report that MCP-2/CCL8 secretion in rheumatoid arthritis synovial fibroblasts is mediated by TLR-2." (PMID 23418602, 2013). "In patients with rheumatoid arthritis, the expression of TLR2, TLR3 and TLR7 is significantly enhanced in synovial fibroblasts." (PMID 24130907, 2013). "For example, the expression of TLR2 and its ligands is elevated in macrophages from the joints of patients with rheumatoid arthritis." (PMID 22025895, 2011). "The aim of this study was to examine the effect of blocking Toll-like receptor 2 (TLR2) in rheumatoid arthritis (RA) synovial cells." (PMID 21345222, 2011). "In line, others have found that intestinal myofibroblasts and synovial fibroblasts of patients with rheumatoid arthritis express TLR2." (PMID 19479087, 2009). "TLR2 (Toll Like Receptor 2) participates in oxidative damage in dairy goats, anti-inflammation in bovine mammary epithelial cells, heat stress immunomodulation in black Bengal goats, and rheumatoid arthritis in humans." (PMID 38336605, 2024). "Moreover, it has been found that celastrol plays a cardioprotective role in rheumatoid arthritis by inhibiting autophagy mediated by TLR2/HMGB1 signaling pathway." (PMID 36034791, 2022). "As a chronic autoimmune disease, the inflammatory condition in rheumatoid arthritis not only enhances bone degradation by raising the crosstalk between osteoclastogenesis and the immune system, but also stimulates TLR2 on osteoblasts and increases the production of RANKL." (PMID 34414191, 2021). "In addition, Rho/ROCK is known to be essential for Toll-like receptor 2 (TLR2)-mediated IL-23 inflammatory immune response in rheumatoid arthritis macrophages." (PMID 34884721, 2021). "For example, data suggest that PRG4 has anti-inflammatory effects (e.g. decrease in expression of a number of pro-inflammatory cytokines and matrix remodelling enzymes, in a CD44 and toll-like receptor 2- and 4-dependent manner) with implications for osteoarthritis, rheumatoid arthritis and gout." (PMID 31361756, 2019). "In rheumatoid arthritis (RA), high levels of serum toll-like receptor 2 (TLR2) and increased TLR2 expression on CD4+ T cells have been observed." (PMID 40963621, 2025). "Research on TLRs and RAGEs in PsA is limited but increasing expression of TLR2, 3, and 4 has been observed in synovial tissues (ST) and SF of patients with rheumatoid arthritis (RA)." (PMID 36508130, 2023).
rheumatoid arthritis (continued). "In rheumatoid arthritis (RA), for example, TLR2 expression occurs in inflamed synovial tissue predominantly at sites of attachment and invasion into the cartilage and bone." (PMID 16277694, 2005). "Studies show that there are high levels of crosstalk between TLR2 and TLR8, which can stimulate the secretion of inflammatory cytokines related to rheumatoid arthritis and other inflammatory diseases." (PMID 35042504, 2022). "TQ was reported to downregulate pro-inflammatory genes such as IL-1, TNF-α, and toll-like receptors (TLR2, TLR4) and attenuate rheumatoid arthritis via the NFkB pathway." (PMID 32793594, 2020). "If all of these regulatory mechanisms fail, hyperactivation of TLR2 can cause autoimmune inflammatory diseases such as atopic dermatitis, acne vulgaris, ischemia, and rheumatoid arthritis (RA); thus, TLR2 inhibitors are essential for the control or treatment of these disorders." (PMID 29976865, 2018). "Antibodies targeting TLR2, OPN-305 and OPN-301, have been proved to be able to abrogate spontaneous cytokine release in rheumatoid arthritis." (PMID 29218046, 2017). "TLR2 and TLR4 receptors are both expressed by osteoarthritic chondrocytes as well as in synovial tissue of rheumatoid arthritis patients." (PMID 25196344, 2014). "Both TLR2 and TLR4 are highly expressed in varying levels of osteoarthritic chondrocytes, as well as in synovial tissue of rheumatoid arthritis patients." (PMID 24457003, 2014). "Our results show that rheumatoid arthritis synovial fibroblasts (RASF) express a series of TLRs, including TLR2, TLR3, TLR4, and TLR9, with the predominant expression of TLR3." (PMID 24936783, 2014). "Conversely, in autoimmune diseases like rheumatoid arthritis (RA), NET-activated dendritic cells (DCs) facilitate T helper 1 (Th1) polarization, while NET-derived histones directly engage TLR2 on T cells, biasing differentiation toward the Th17 lineage, particularly in periodontitis." (PMID 40442839, 2025). "In addition, expression levels of Mpeg1, Enpp2, Tlr2, CD14, and Lyz2 were examined in the synovial tissues of patients with rheumatoid arthritis (RA) and persistent inflammatory, recurrent, and relapsing arthritis (PIRRA)." (PMID 40787440, 2025). "In our analysis, the hub-DEGs TLR2 and CXCL2 significantly enriched the rheumatoid arthritis pathway which indicates that these genes may have the antagonized property against the COVID-19 infection." (PMID 35277538, 2022). "Because of the ability of RP105 in blocking TLR2 and TLR7, it can be speculated that RP105 could regulate osteoclastogenesis in rheumatoid arthritis via a TLR2/TLR7." (PMID 34414191, 2021). "Stimulation of TLR2 and TLR4 could enhance the inflammatory response in rheumatoid arthritis (RA), and the expression of TLRs was found to be associated with the incidence of inflammatory bowel disease (IBD) and the pathogenesis of Behcet’s disease." (PMID 35069523, 2021). "Also, a recent study reported that TQ exerts anti-inflammatory effects by reduction of TNF-α, TLR-2, TLR-4, and Interleukin-1 in rheumatoid arthritis." (PMID 32793594, 2020). "All of these data suggest that IRAK-4 may be a suitable target for inflammatory diseases involving multiple receptors including IL-1R (rheumatoid arthritis (RA) and osteoarthritis (OA)), IL-18R (inflammatory bowel disease (IBD)), TLR2, 4 (RA), and TLR7, 9 (SLE)." (PMID 19689377, 2009). "For instance, the degradation products of high-molecular-weight hyaluronic acid activate TLR2/4 and cluster of differentiation 44 (CD44), thereby promoting the inflammatory process in obesity and rheumatoid arthritis (RA)." (PMID 40877572, 2025). "Also, HMGB-1 is a mediator of inflammation, as a ligand of TLR2, TLR4, and RAGE, that can promote ECM degradation and activate cell autophagy, and it has been involved in various autoimmune diseases (e.g. rheumatoid arthritis)." (PMID 41225346, 2025).
rheumatoid arthritis (continued). "This study investigates the role of Toll-like receptor 2 (TLR2) in the regulation of migratory and invasive mechanisms in rheumatoid arthritis (RA)." (PMID 26055925, 2015). "It is becoming clear that TLRs are involved in systemic autoimmune disorders, because it was recently demonstrated TLR2 and TLR4 are involved in rheumatoid arthritis (RA) and TLR9 in systemic lupus erythematosus." (PMID 18234118, 2008). "An increase in expression of TLR2 and TLR4 has also been observed in the synovial membrane collected from patients with other SpAs, including with PsA and undifferentiated SpA, compared to patients with rheumatoid arthritis (RA) and osteoarthritis (OA)." (PMID 29283375, 2017). "The involvement of the TLR signaling in rheumatoid arthritis (RA) was shown on mice lacking MyD88 or TLR2 that were resistant to the induction of the disease." (PMID 23305364, 2012). "In rheumatoid arthritis patients, CD16+ monocytes expressed higher TLR2 than CD16− monocytes while no TLR4 expression level difference between the two monocyte subsets." (PMID 38660059, 2024). "Yan et al42 found that lncRNA HIX003209 did not directly bind to TLR2, TLR4 and NF‐κB; however, it promoted TLR4/NF‐κB expression in macrophages through the sponge miR‐6089, which was critical for the development of rheumatoid arthritis." (PMID 33728802, 2021).